GABRA2 (gamma-aminobutyric acid type A receptor subunit alpha2)
Diseases named in the same sentence as GABRA2 in open-access papers (continued):
Sharing a sentence is not in itself a finding about the gene and the disease.
GABRA2 also shares sentences with these, for which no sentence is quoted: alcoholism (11 papers); depression (6); breast carcinoma (2); conduct disorder (2); developmental delay (2); generalized epilepsy (2); hyperekplexia (2); anxiety disorder (1); autism spectrum disorder (1); bipolar disorder (1); central nervous system disorder (1); cognitive deficits (1); congenital nystagmus (1); early-onset epilepsy (1); Focal cortical dysplasia (1); genetic generalized epilepsy (1); infantile epileptic encephalopathy (1); intellectual disability syndrome (1); medulloblastoma (1); myopia (1); neurodegenerative disease (1); neurological disorders (1); psychotic disorder (1); temporal lobe epilepsy (1); tuberous sclerosis (1).